EGFR (epidermal growth factor receptor)
Diseases named in the same sentence as EGFR in open-access papers (continued):
Sharing a sentence is not in itself a finding about the gene and the disease.
squamous cell carcinoma (787 papers, 1987 to 2026). A carcinoma arising from squamous epithelial cells. "IPF-associated tumors had a higher proportion of carrying EGFR wild-type, occurring in the lower lobe of the lung and developing adenocarcinoma and squamous cell carcinoma." (PMID 40507634, 2025). "In contrast, our study included a significant portion of patients with squamous cell carcinoma and those with EGFR and KRAS mutations, which are likely contributing to this difference and warrant further clinical and translational research for confirmation." (PMID 41245885, 2025). "Squamous cell carcinoma, typically central, is strongly associated with smoking and expresses p40 and p63 while showing low rates of EGFR mutations." (PMID 40827171, 2025). "A previous study reported that first‐generation EGFR‐TKIs were less effective for EGFR‐mutated squamous cell carcinoma than for adenocarcinoma, with an objective response rate of 31.6% and median progression‐free survival (PFS) of 3.08 months." (PMID 40620186, 2025). "Squamous cell carcinoma was identified in 96 (48%) patients, with EGFR mutations present in 35 (18%), and KRAS mutations in 65 (34%)." (PMID 41245885, 2025). "EGFR mutations have been reported in 47.9% of adenocarcinomas and 4.6% of squamous cell carcinomas in Asian populations, and 19.2% of adenocarcinomas and 3.3% of squamous cell carcinomas in Western populations, and are rare in squamous cell carcinomas." (PMID 40620186, 2025). "Regarding EGFR mutations, we found a patient with squamous cell carcinoma who tested positive with the Cobas® assay (insertion exon 20) and not mutated by NGS." (PMID 40591555, 2025). "In patients with squamous cell carcinoma, approximately 30% of tests for EGFR, ALK, and RET mutations were positive, which confirms the importance of testing at least a preselected subgroup of patients." (PMID 39518907, 2024). "A-431 human epidermoid carcinoma cells are known to express high levels of EGFR and are often used to study cancer-associated cell signaling events." (PMID 38429428, 2024). "The presence of MCPyV DNA has also been significantly correlated with cancer prognosis in subgroups of NSCLC patients with pN0 stage, squamous cell carcinoma or EGFR mutations." (PMID 39031987, 2024). "Similar to our findings in this study, EGFR inhibition has been shown to increase cellular cohesion in squamous cell carcinomas, whereas in keratinocytes, EGFR inhibition protected against DSG3 autoantibody–induced loss of keratinocyte adhesion." (PMID 36795511, 2023). "Squamous cell carcinoma and PD-L1 expression < 1%, and female sex and EGFR mutations were significantly associated with an increased risk of LR and DM." (PMID 36149029, 2023). "The last point of view coincides with squamous carcinoma genomic atlas which shows that EGFR is seldom mutated SQC in lung." (PMID 38008767, 2023). "Previous randomized clinical trials have also found a bigger effect in patients with squamous carcinomas, presumably associated with the greater expression of unmutated EGFR in this tumor type." (PMID 38304035, 2023). "To date, the transformation from adenocarcinoma to squamous cell carcinoma associated with EGFR-TKI use remains poorly reported." (PMID 36158654, 2022). "Epidermal growth factor receptor (EGFR) mutation is currently the most common target; approximately 10% to 15% of the Caucasian population and more than 50% of Asian patients with non-squamous cell carcinoma carry this mutation." (PMID 35935943, 2022). "In the case of adenocarcinoma (even in dimorphic combination with squamous cell carcinoma), a molecular genetic assay of EGFR mutations (18–21 exons), BRAF, V600E, ALK, and ROS1 is recommended." (PMID 35982978, 2022). "One mutation was detected in KRAS (G12/G13) and 3 in EGFR (2 L858R, 1 S768I) for three patients with squamous cell carcinoma with a smoking history, and one patient with SCLC." (PMID 36413862, 2022).
squamous cell carcinoma (continued). "The EGFR Q787Q polymorphism was also identified as a poor prognostic factor in advanced squamous cell carcinoma and metastatic colon cancer treated with an anti-EGFR antibody." (PMID 35387120, 2022). "Different subtypes of EGFR mutations in primary NSCLC patients were evaluated, and more EGFR mutations were found in adenocarcinoma than in squamous cell carcinoma and large cell carcinoma, and." (PMID 35265073, 2022). "Afatinib is approved for the treatment of NSCLC either with activating EGFR mutation or in squamous cell carcinoma under or after progression on platinum-based chemotherapy and is efficacious in tumor models at dosages from 20 mg/kg or higher once a day27." (PMID 35039644, 2022). "By histological analysis, the majority of tumors were adencarcinoma (52/78, 66.7%) or squamous carcinoma (19/78, 24.4%), moderately differentiated (33/63, 52.4%), and positive for EGFR mutation (19/30, 63.3%)." (PMID 35332177, 2022). "In the two subtypes of NSCLC, adenocarcinoma was significantly associated with higher prevalence of EGFR exon 19 deletion and L858R mutation, compared to squamous cell carcinoma." (PMID 35061839, 2022). "They found that TKI sensitivity increased up to 70-fold in squamous cell cancers with the EGFR Q787Q polymorphism." (PMID 35387120, 2022). "This study found that the incidence of EGFR mutation in women, adenocarcinoma, and non‐smokers is significantly higher than that in men, squamous cell carcinoma, and smokers, and the differences between these groups are statistically significant." (PMID 35081265, 2022). "On the other hand, in male patients, adenocarcinoma was associated with higher prevalence of EGFR exon 19 deletion and L858R, compared to squamous cell carcinoma." (PMID 35061839, 2022). "The significantly different expression of LINC00240 only in squamous cell cancer provides clues to explaining the augmented EGFR expression, drawing on the findings of high expression of EGFR and marginal EGFR mutations in squamous cell cancer." (PMID 33422052, 2021). "Although the overexpression or mutation of EGFR levels has proven to be a valid predictor of treatment outcome, the response rates in selected patients remain chemoresistance or poor prognosis in squamous cell carcinomas as well as other malignancies." (PMID 33602237, 2021). "The epidermal growth factor receptor gene (EGFR) which lies on chromosome 7p11.2 is implicated in various cancers with some of the well-established examples including squamous cell carcinoma, epithelial cell line cancers, and GBM." (PMID 34671307, 2021). "Adenocarcinoma tumors were mostly pan-wild type (36.5%), KRAS mutated (35.4%), and EGFR mutated (16.3%) while squamous cell carcinoma tumors were even more predominantly pan-wild type (85.5%)." (PMID 34917263, 2021). "The histological transformation from epidermal growth factor receptor (EGFR)-mutated adenocarcinoma (ADC) to squamous cell carcinoma (SCC) after tyrosine kinase inhibitor (TKI) treatment is rare." (PMID 34169002, 2021). "EGFR overexpression or amplification occurs more frequently in squamous cell carcinoma than in adenocarcinoma, but EGFR mutations occurs mostly in adenocarcinoma." (PMID 33422052, 2021). "According to the data from previous studies, the EGFR mutation prevalence in squamous cell carcinomas is very low, ranging from 2% to 7%." (PMID 34696229, 2021). "Treatment of human A431 epidermoid carcinoma cells with 20 μM TF3 for 1 h caused internalization of EGFR in EGFR-overexpressing cells as determined with confocal microscopy." (PMID 33668434, 2021).
squamous cell carcinoma (continued). "Real-time polymerase chain reaction (PCR) analysis showed that the adenocarcinoma had an epidermal growth factor receptor (EGFR) mutation presenting as point mutation L858R, while the squamous cell carcinoma suffered from ALK fusion." (PMID 32727606, 2020). "Chest computed tomography (CT) scan showed a tumor shadow, and CT-guided lung biopsy revealed squamous cell carcinoma harboring an EGFR mutation." (PMID 32291904, 2020). "An unreported case of stage III squamous cell carcinoma with synchronous occurrence of EGFR exon 19 deletion (19Del) and T790M mutation." (PMID 32667739, 2020). "The cohort included squamous cell carcinoma (n = 8), adenocarcinoma (n = 9), large cell neuroendocrine carcinoma (n = 3), and adenosquamous carcinoma (n = 1) by histology; 1 tumor harbored an EGFR activating mutation." (PMID 31959763, 2020). "EGFR overexpression in squamous cell carcinoma in the head and neck areas is known to be associated with a poor prognosis." (PMID 32942549, 2020). "Among patients with squamous cell carcinoma, the EGFR mutation rate was 8.3% (9/109) and the ALK rearrangement rate was 3.7% (4/109)." (PMID 31144459, 2019). "Because of the relatively high mutation rate, patients with squamous cell carcinoma should also be routinely tested to determine their EGFR and ALK statuses." (PMID 31144459, 2019). "Among patients with squamous cell carcinoma, the EGFR mutation rate was 8.3% and the ALK rearrangement rate was 3.7%." (PMID 31144459, 2019). "EGFR mutations are the most common genetic lesions in adenocarcinoma but are very rare in squamous cell carcinoma." (PMID 29849818, 2018). "Recently, also tumour-specific mutations have been reported, such as EGFR exon 20 mutations in 88% inverted papilloma and in 77% of squamous cell carcinoma associated with inverted papilloma, and KRAS mutations in oncocytic papillomas." (PMID 29507386, 2018). "An EGFR mutation analysis was successfully performed in 296 cases (230 adenocarcinomas, 59 squamous cell carcinomas, 4 adenosquamous carcinomas, 3 large-cell carcinomas)." (PMID 28704499, 2017). "Using the A-431 cell line, a human epidermoid carcinoma cell type rich with EGFR, he discovered that the addition of EGF caused the phosphorylation of the EGFR." (PMID 28513565, 2017). "Histopathologically, 78 of the 80 EGFR-mutated cases were adenocarcinoma, and the rest were adenosqumaous carcinoma (n = 1) and squamous cell carcinoma (n = 1)." (PMID 28704499, 2017). "Acquired resistance of xenograft models of squamous cell carcinoma to anti-EGFR monoclonal antibodies associates with enhanced levels of VEGFA48." (PMID 28383032, 2017). "Taking into account the different types of cancer can cause different levels of free nucleic acid, adenocarcinoma, squamous cell carcinoma, and large cell lung cancer groups were established to detect EGFR mutation DNA and cfDNA in plasma." (PMID 28382702, 2017). "It should be noted that EGFR mutations were detected in 21.9% (23/105) of the patients with adenocarcinoma and 14.3% (2/14) of the patients with squamous cell carcinoma." (PMID 29097733, 2017). "With respect to the histological type, the EGFR mutation rate in adenocarcinomas was significantly higher than that in squamous cell carcinomas, which is consistent with other reports." (PMID 27322143, 2016). "Histologically, the EGFR mutation rate in adenocarcinomas was significantly higher than that in squamous cell carcinomas." (PMID 27322143, 2016). "In patients with adenocarcinoma, adenosquamous and squamous-cell carcinoma, 41.8% (493/1178), 30.9% (21/68) and 6.6% (12/181) harbored EGFR-TKIs sensitive mutations (p < 0.001), respectively." (PMID 27992557, 2016). "It has been reported that adenocarcinoma and squamous cell carcinoma components can possess the same EGFR mutation, suggesting that the histologic origin of adenosquamous lung carcinoma can be monoclonal." (PMID 27623437, 2016).
squamous cell carcinoma (continued). "EGFR Mutations were detected in 38.5% (218/566) adenocarcinoma cases, 4.3% (15/352) squamous cell carcinoma, 42.1% (8/19) adenosquamous carcinoma and 9.5% (4/42) large cell lung carcinoma." (PMID 27072585, 2016). "In this study, although the rate of EGFR-TKIs sensitive mutation in squamous cell carcinoma and adenosquamous carcinoma was obviously lower than with adenocarcinoma, but it is clear that the rate is higher than other geographical regions." (PMID 27992557, 2016). "Elevated Cyfra21-1 reliably predicted worse DFS and OS in EGFR-mutated squamous cell carcinoma patients." (PMID 27072585, 2016). "Previous studies have found that, even with EGFR mutations in squamous cell carcinoma, it is still the inferior efficiency treatment with EGFR-TKIs than adenocarcinoma with EGFR mutations." (PMID 26624882, 2016). "The frequency of EGFR gene mutations in German squamous cell carcinoma (SCC) patients ranged from 0 to 3.5 %." (PMID 25086987, 2015). "Craniotomy with resection revealed a metastatic poorly differentiated squamous cell carcinoma harboring the same EGFR mutation as the original tumor." (PMID 26366316, 2015). "Overexpression of EGFR is associated with aggressive behaviour including increased proliferation, metastasis, and therapeutic resistance in squamous cell carcinoma (SCC) of the oral cavity and oropharynx." (PMID 25918252, 2015). "Firstly 9% of our samples were squamous cell carcinoma, which have much lower incidence of EGFR mutations than ADC." (PMID 24956168, 2014). "The patient requested treatment with epidermal growth factor receptor (EGFR)-tyrosine kinase inhibitors (TKIs) because dozens of patients with squamous cell carcinoma and EGFR mutations responded well to TKIs at our institute." (PMID 24885608, 2014). "The adenocarcinoma EGFR gene mutation rate (77/139) was significantly higher than that of squamous cell carcinoma (8/36) and large cell carcinoma (0/1) (χ2=12.454; P=0.002)." (PMID 25013503, 2014). "The current consensus recommends testing all newly diagnosed patients with advanced stage non squamous lung cancer, as well as some patients with squamous cell carcinoma with clinical features associated with higher prevalence of EGFR mutations in East Asia." (PMID 23468851, 2013). "The overall frequency of EGFR mutations in adenocarcinoma population was 26% as compared to 3.8% in squamous cell carcinomas." (PMID 24124538, 2013). "The rate of detected EGFR mutation in the adenocarcinoma subgroup (n = 49) was 40.8%, which was significantly higher than 7.9% in the patients with squamous cell carcinomas and 14.3% in the NSCLC NOS." (PMID 24205040, 2013). "Taken together, this study emphasizes that EGFR mutation test for squamous cell carcinoma need to as well be considered as a routine practice, as recommended for ALK mutations with comparable incidence at around 5%." (PMID 24124538, 2013). "We found EGFR mutation rate of 3.8% in this largest cohort of squamous cell carcinoma study reported so far, n = 103, which is surprisingly more similar to incidence as observed in the west." (PMID 24124538, 2013). "Twenty-six patients were enrolled, all of whom were diagnosed with adenocarcinoma with EGFR mutations (19del: 16, L858R: 10) except one (squamous cell carcinoma with 19del)." (PMID 24369725, 2013). "In contrast, our study found that 6 out of 54 patients (11.1%) with squamous cell carcinoma had EGFR mutations, with an even higher prevalence in the subgroup of never smoker patients with squamous cell carcinoma (2 out of 12, or 16.7%)." (PMID 23468851, 2013). "Patients with adenocarcinoma (41.1%) had significantly higher proportions of positive EGFR mutation tests compared to those with squamous cell carcinoma (11.1%) (P<0.001)." (PMID 23468851, 2013). "In pre-Neoadj-Chemo samples, the EGFR mutation rate was 55.6% (15/27) in adenocarcinoma, which is higher than measured in patients with squamous cell carcinoma (17.1% [6/35])." (PMID 23520442, 2013).
squamous cell carcinoma (continued). "The mutation rates of EGFR in adenocarcinoma (AC), squamous cell carcinoma (SCC), and large cell carcinoma (LCC) were 40.3% (140/347), 4.4% (6/144), and 3.8% (1/26), respectively (X2 = 73.595, P<0.0005, Chi-square test, 2-sided)." (PMID 22768234, 2012). "There is emerging evidence that increased EGFR expression is associated with an increased miR-7 level, at least in squamous cell carcinomas." (PMID 22529906, 2012). "Mutations in exons 18-21 of EGFR TK domain were detected in 19 (23%) of the 81 NSCLCs in which there were 12 adenocarcinomas, three bronchioloaveolar carcinomas, two squamous cell carcinomas, one adenosquamous carcinoma, and one other type of NSCLC." (PMID 20459863, 2010). "Squamous cell carcinomas of the oro-, hypopharynx and larynx often show an overexpression of epidermal growth factor receptors (EGFR), which is described to be associated with a poor prognosis." (PMID 21108850, 2010). "This research was carried out to determine if conjunctival squamous cell carcinoma harbors human papillomavirus DNA and is associated with activation of the EGFR signaling pathway." (PMID 20498858, 2010). "EGFR mutational status was assessed in the patient tumor DNA of the conjunctival squamous cell carcinoma through DNA sequencing analysis." (PMID 20498858, 2010). "It is known from studies in other tumour types (e.g. NSCLC) that somatic mutations in the tyrosine kinase domain of EGFR are much more common in adenocarcinomas than in squamous cell carcinoma." (PMID 20459770, 2010). "These included 12 adenocarcinomas, 9 squamous cell carcinomas and 1 large cell carcinoma, all examined for known EGFR/KRAS/NRAS/HRAS/PI3K mutations." (PMID 19806209, 2009). "Squamous cell carcinoma harbouring an EGFR mutation is rarely seen but has been previously reported." (PMID 18283321, 2008). "Epidermal growth factor receptor (EGFR) overexpression has been associated frequently with squamous cell carcinomas (SCC) and SCC cell lines." (PMID 8080726, 1994). "Notably, our cohort was predominantly squamous cell carcinoma, in which EGFR/ALK mutations are rare, minimizing their likely impact." (PMID 40623866, 2025). "However, regarding the histological type of the tumor, adenocarcinomas were more frequent than squamous cell carcinomas in patients with EGFR mutations (85.7% vs. 14.3%, p = 0.046)." (PMID 39199673, 2024). "Emphysema’s inclusion might stem from the recognized association between adenocarcinoma, which has a higher incidence of EGFR mutations, and emphysema, compared to squamous cell carcinoma." (PMID 39650554, 2024). "Non-squamous cell carcinomas that are positive for EGFR mutations are susceptible to developing DM." (PMID 36149029, 2023). "Some large studies showed an association of EGFR overexpression with younger age, histological type (more frequently and strongly overexpressed in squamous cell carcinomas than adenocarcinomas and adenosquamous carcinomas), increasing tumour size, lymph node metastases and recurrence." (PMID 38414930, 2023). "Although these first- and new generation TKIs improved the survival for patients with non-squamous cell carcinoma and EGFR or ALK mutation, these patient populations accounted for a low percentage of the overall NSQ group (approx. 10% and 4% based on clinical references)." (PMID 37860193, 2023). "In addition, two cases in the responder group showed transformation into squamous cell carcinoma revealed by rebiopsies during the treatment course, and the EGFR subtype in both cases was L858R mutation." (PMID 34904383, 2022). "Furthermore, we showed that CBD and CBG inhibit EGF-induced EGFR-TK activity and cause inhibition of epidermoid carcinoma A431 ​cell growth, which can lead to apoptotic death." (PMID 36568260, 2022).